CCL2 (C-C motif chemokine ligand 2)
Diseases named in the same sentence as CCL2 in open-access papers (continued):
Sharing a sentence is not in itself a finding about the gene and the disease.
myocardial infarction (129 papers, 2007 to 2025). Gross necrosis of the myocardium, as a result of interruption of the blood supply to the area, as in coronary thrombosis. "Several studies have shown that higher levels of CCL2 increase the risk of coronary artery disease and myocardial infarction." (PMID 37422588, 2023). "A 2-year survival analysis showed that low CCL2 serum levels was highly associated with myocardial infarction." (PMID 32257639, 2020). "Smoking has also been shown to have impact on various diseases and has been found to be associated with CCL2 polymorphism and their levels in patients of myocardial infarction." (PMID 29664944, 2018). "Polymorphisms in the MCP1/Ccl2 promoter, thought to increase MCP1/Ccl2 expression, have been associated with CAD, chronic stable angina, and myocardial infarction." (PMID 40753563, 2025). "CCL2 plasma levels and PMo numbers/frequency are also altered in endotoxemia, myocardial infarction, and malaria." (PMID 37490346, 2023). "In a small group of 83 patients with acute myocardial infarction and 38 patients with stabile angina, both CCL2 and CC chemokine, regulated upon activation, normal T cell-expressed and presumably secreted (RANTES) serum levels were analyzed." (PMID 33540898, 2021). "An elegant study by Liu and colleagues demonstrates increased levels of CCL2 (Chemokine CC-motif ligand 2) in plasma, platelets, and thrombus material of patients with myocardial infarction." (PMID 31783528, 2019). "Single nucleotide polymorphisms (SNPs) in the promoter of CCL2, CCL2-2518G, and in the open reading frame of CCR2, CCR2-V64I, have been associated with increased risk of myocardial infarction in humans." (PMID 24741577, 2014). "Additionally, we analyzed dual-function cytokines, such as CCL2, which recruits monocytes during the early phases of myocardial infarction and supports their transition to reparative phenotypes during later stages." (PMID 40661150, 2025). "Elevated CCL2 levels attract monocytes to the sites of plaque formation, where they differentiate into macrophages, contributing to chronic inflammation and plaque instability, potentially leading to myocardial infarction." (PMID 39201480, 2024). "Notably, CCL2 has been demonstrated to have a significant role in mitigating left ventricular dysfunction and remodeling post-myocardial infarction (MI)." (PMID 38673859, 2024). "Moreover, CCL2 has been shown to play an important role in preventing left ventricular dysfunction and remodeling after myocardial infarction." (PMID 37508517, 2023). "Based on the inflammatory and fibrotic markers commonly observed in response to myocardial infarction and development of heart failure, we assessed the expression of mRNA for Tnfa, Il1b,Il6, Il18, Ccl2, Ccl3, Cxcl1, Cxcl2, Col1a1, Col3a1, Postn, and Tlr4 at 1 and 3 months." (PMID 35411847, 2022). "Therefore the aim of current study was to evaluate the concentrations of chemokines RANTES and CCL2 in acute myocardial infarction (AMI) patients and stable angina (SA) subjects on their admission to the hospital, as compared to healthy control subjects." (PMID 31396527, 2019). "Likewise, the association between the overexpression of CCL2/MCP1 in MHC-MCP1 mice and improved cardiac tissue repair after myocardial infarction suggests that this chemokine plays a role in tissue remodeling after damage." (PMID 27525724, 2016). "Both CCL2 and CCL3 have been implicated in cardiac pathologies: CCL2 (MCP-1) is a well-known chemokine involved in recruitment of leukocytes and regulated after myocardial infarction (Birdsallet al, 1997)." (PMID 25193973, 2014). "It is also suggested that CCL2 may have influence on a number of processes occurring in the course of myocardial infarction, such as myocardial necrosis, apoptosis, leukocyte recruitment, treatment of myocardium, and formation of scars, as well as angiogenesis." (PMID 31396527, 2019).
myocardial infarction (continued). "Its primary action targets IL-10, with the protein–protein interactions analysis indicating interactions between IL-10 and key inflammatory mediators—IL-1β, IFN-γ, CCL2, TNF, and TGF-β1—during acute myocardial infarction and cardiac fibrosis." (PMID 39200761, 2024). "Inhibition of monocyte recruitment by blocking the CCL2 and CCR2 signaling pathways reduces excessive inflammation, myocardial infarction and atherosclerosis is protective in a sclerosis-like mouse model." (PMID 36247005, 2022). "During the acute phase of myocardial infarction (MI) in the adult heart, resident macrophages recruit leucocytes (by secreting CXCL2 and CXCL5) and monocytes (by secreting CCL2) to the ischemic area." (PMID 33130914, 2021). "CCR2, the receptor for CCL2 and CCL11, is expressed on HSPCs and CCR2-positive HSCs were found to be the most upstream contributor to emergency myelopoiesis, after myocardial infarction." (PMID 33003401, 2020). "In a study about myocardial infarction, cardiomyocyte-derived large EVs, but not small EVs, modulate the release of CCL2, CCL7, and IL-6 from cardiac monocytes." (PMID 40995365, 2025). "Taken together, these findings suggested that IFN-β-responsive MICFs recruit monocytes/macrophages after myocardial infarction, and macrophages secreted IFN-β phosphorylate STAT1 in MICFs which further increases the expression of Ccl2, Ccl7, and Ccl12, forming a positive feedback loop." (PMID 38530808, 2024). "Reduced transcription of CCL2, expression of CD163+ macrophages, and modulation of immune response factors, including IL-1, PBMC influx, TNF-α, GM-CSF levels, and CD73+ and CCR2+ monocytes, further support EV’s therapeutic potential for myocardial infarction." (PMID 38790361, 2024). "While there is typically a small number of resident macrophages in the heart that participate in cardiac homeostasis, after myocardial infarction, many circulating monocytes infiltrate the infarcted myocardium, facilitated by chemotactic proteins like MCP-1/CCL2." (PMID 38170009, 2023). "CCR2, the main receptor of CCL2, exhibits mild expression in the human heart, and a single-nucleotide polymorphism of the CCR2 gene is associated with myocardial infarction and heart failure, but not with coronary atherosclerosis, in human patients." (PMID 35260907, 2022). "Interestingly, IL-1, IL-6, CCL2, and CCL3 expression was reduced, whereas Arg1, IL4Rα, and IL-10 expression were increased in macrophages incubated with exosomes derived from the myocardial infarction group." (PMID 35548775, 2022). "Following a myocardial infarction, classical monocytes are recruited within the first few hours, and their egression from the bone marrow is in principle controlled by the chemokine receptor CCR2 and its ligands CCL2 (or MCP-1) and CCL7 (or MCP-3)." (PMID 27478854, 2016). "Previous studies have demonstrated that CCL2 expression is elevated in infarcted myocardial tissue, promoting cardiac regeneration through the activation of STAT3 signaling, thereby highlighting its potential therapeutic role in myocardial infarction (MI) and related heart failure." (PMID 40342964, 2025). "During inflammatory processes, monocyte recruitment, which is tightly regulated by interaction between CCL2 and CCR2, could be reduced using silencing of the chemokine CCR2 with nanoparticles, as already experimentally tested in experimental myocardial infarction." (PMID 30177883, 2018). "For example, pyridostigmine bromide (PYR) can reduce the chemotactic factor CCL2/7 (C-C chemokine ligand), leading to a reduction in cardiac MHC-IIhiCCR2+ macrophage infiltration and increases in the numbers of M2 macrophages and Treg cells in mouse models of myocardial infarction (MI)." (PMID 40337863, 2025). "In addition, CCL2, also known as monocyte chemoattractant protein-1 (MCP-1), has a higher serum level in ST-segment elevation myocardial infarction (STEMI) patients, but lower plasma levels in MI patients without collateral circulation." (PMID 37056987, 2023).
Hepatic steatosis (126 papers, 2010 to 2026). Steatosis is a term used to denote lipid accumulation within hepatocytes. "In control diet fed mice, Nrf2 deficiency was nonconsequential, while Nrf1 and combined deficiency exacerbated the effect, as demonstrated by hepatic steatosis as well as significant or trending increases in hepatic triglyceride and expression of Ccl2, Ccnb1, Col1a1, Col3a1, Ihh, and Tnfrsf12a." (PMID 39125617, 2024). "Indeed, pharmacological antagonist of CCR2 reduced liver steatosis in obese and diabetic mice (db/db), and CCL2 deficiency reduced the accumulation of hepatic triglycerides in HFD and db/db mice." (PMID 28115795, 2017). "In addition, adenoviral overexpression of CCL2 in the liver caused the accumulation of myeloid cells coincident with hepatic steatosis." (PMID 23964268, 2013). "Thus, interruption of the CCL2/CCR2 pathway may provide an effective therapeutic strategy for attenuating the progression of liver steatosis and of associated metabolic disorders." (PMID 24646914, 2014). "Subsequent studies in CCL2-deficient mice suggest that CCL2 plays a minimal role in glucose metabolism and insulin sensitivity in mice fed a normal diet, but is important for pathogenic macrophage infiltration into adipose tissue, insulin resistance, and hepatic steatosis induced by a high-fat diet." (PMID 20936118, 2010). "Previous studies have shown that macrophage recruitment via increased expression of monocyte chemoattractant protein 1 (MCP-1, also referred as CCl2) in hepatocytes enhanced hepatic steatosis and inflammation in alcoholic and nonalcoholic liver disease." (PMID 38553537, 2024). "Another study has shown that the expression level of CCL2 in the liver positively correlates with the severity of fatty liver disease." (PMID 39568749, 2024). "Mice fed with the OYC-NASH2 diet for 3 weeks showed severe hepatic steatosis and inflammatory cell infiltration, and the expression of its related genes, such as Tnf, Ccl2, and Lgals3, was significantly increased at 3 weeks." (PMID 37509405, 2023). "In particular, higher levels of CCL2 have been identified in NASH subjects in comparison with simple fatty liver." (PMID 35740337, 2022). "Pharmacological inhibition of CCR2 and genetic deletion of CCL2 reduced liver steatosis in obese mice." (PMID 31921154, 2019). "The treatment with APs or atorvastatin induced a remarkable reduction in the atherosclerotic lesions and hepatic steatosis and decreased the levels of low-density lipoprotein, triglyceride, CCL-2 and VCAM-1 levels in the plasma." (PMID 26305254, 2015). "CCR2-dependent recruitment of myeloid cells to the liver and CCL2-dependent development of hepatic steatosis were also demonstrated by other studies." (PMID 23964268, 2013). "We confirmed that the effect of fat in the pathogenesis of fatty liver disease is influenced by the amount of available CCL2 and that the linkage between chemokines and hepatic lipid metabolism is plausible." (PMID 24453432, 2013). "Interestingly, in Cluster 4 which was consistent with the progression of liver steatosis, DEGs were related to inflammation and included major cytokines and chemokines, such as Ccl2 and Cxcl1." (PMID 40687776, 2025). "The enrichment of Bacteroides acidifaciens and Blautia producta via prebiotic inulin consumption synergistically elevates the concentration of acetate in mice fed a high-fat/high-fructose/high-cholesterol diet, which remarkedly suppresses hepatic steatosis and fibrosis in mice via CCL2 expression." (PMID 35327352, 2022). "For example, inflammatory cytokine CCL2 could exacerbate hepatic steatosis in chronic hepatic injury." (PMID 35837283, 2022). "LSECs facilitate the hepatic recruitment of monocytes through the increased production of CCL2, and they could also display anti-inflammatory properties to prevent KC activation in the progression of fatty liver disease." (PMID 34956171, 2021).
Hepatic steatosis (continued). "This could be explained by the fact that CCL2 and its receptors are upregulated in the liver, and this can promote macrophage accumulation in the liver and adipose tissue, which may lead to liver steatosis, hepatitis, and fibrosis." (PMID 33042108, 2020). "Of note, F4/80 stained cells were more frequent in KO mice, a finding that merits further study because these results could represent a change in function and could be responsible for the differential effects of CCL2 in liver steatosis." (PMID 24453432, 2013). "However, feeding with an HFD induced more severe hepatic steatosis and fibrogenesis in Foxo1/3/4 triple knockout mice compared to wild-type mice via upregulating profibrotic genes such as C-C motif chemokine ligand 2 (CCL2), alpha-1 type I collagen (Col1A1), and TGF-β." (PMID 34359642, 2021). "However, while treatment with the CCL2 inhibitor mNOX-E36 resulted in a decrease of monocyte/macrophage infiltration and hepatic steatosis in the murine models of carbon tetrachloride- and MCD diet-induced hepatic injury, mNOX-E36 application was not able to alter fibrosis progression." (PMID 24646914, 2014). "Therefore, the effect of CCL2 under these conditions is directly related to the amount of tissue CCL2 disposal; the absence of CCL2 prevents liver steatosis, and overexpression of CCL2 predisposes the liver to steatosis." (PMID 24453432, 2013). "In addition, pharmacologically inhibiting CCL2 expression in mice with CCl4 or methionine-choline-deficient (MCD) diet-induced chronic liver injury suppresses monocyte/macrophage migration into the injury liver, resulting in amelioration of hepatic steatosis and inflammation." (PMID 34681695, 2021). "MCP1, also known as CCL2, regulates macrophage activation, proinflammatory responses, and hepatic steatosis in the liver." (PMID 30893931, 2019). "Others have shown that interleukin-1 receptor antagonist is overexpressed in WAT of obese humans and that CCL2/MCP-1 contributes to adipose IR and the development hepatic steatosis." (PMID 20098690, 2010). "In addition, quantitative PCR revealed a decrease upon Cpd17 treatment in inflammatory markers F4/80, CCL2 and intracellular cell adhesion molecule (iCAM1), HSC‐specific marker α‐SMA and liver steatosis marker CCAAT‐enhancer‐binding proteins (C/EBP) (Fig EV4)." (PMID 35833384, 2022). "It has been reported that in AT, the overexpression of CCL2/MCP-1 elevates macrophage recruitment, whereas knockdown reduces the accumulation of proinflammatory macrophages, providing protection from IR and hepatic steatosis." (PMID 33671547, 2021). "Levels of CCL2 and CCL19 are increased in the serum of patients with fatty liver disease." (PMID 34956171, 2021). "CCL2/CCR2 has been identified as chemokines that promote monocyte infiltration into the injured liver; therefore, CCL2/CCR2 is likely to be applied in clinics in the treatment of fatty liver disease in the future." (PMID 34956171, 2021). "Third, as inflammation is a critical factor in the progression of fatty liver disease from simple steatosis to NASH, we also analyzed two inflammatory marker genes - adhesion G protein-coupled receptor E1 (Adgre1, also named Emr1 or F4/80) and chemokine (C-C motif) ligand 2 (Ccl2, also named MCP-1)." (PMID 28300161, 2017).
depression (125 papers, 2007 to 2025). "In a study, higher baseline levels of the pro-inflammatory cytokines IFN-γ and CCL-2 were associated with poorer response to escitalopram monotherapy and adjunctive aripiprazol in major depressive disorders." (PMID 40042668, 2025). "For example, CCL2 (MCP-1), a chemokine involved in a range of neurobiological processes, has been associated with depression brain-immune system communication and suggested as a potential antidepressant target (Curzytek and Leśkiewicz, 2021)." (PMID 39055655, 2024). "As cytokines were tightly associated with the onset of depression, we tested the expression levels of inflammatory cytokines and found that Ccl2 was the most significantly upregulated in the Ninj2‐deficient oligodendrocytes, compared to the WT cells." (PMID 34787377, 2022). "An increase in expression of the inflammatory genes NFKβ, MMP9, CCL2 in the cortex, the region most associated with depression, was observed in obese rats." (PMID 34714995, 2021). "Data on associations between the chemokine CCL2 and the adipokine adiponectin with depression are relatively scarce." (PMID 29520075, 2018). "Paracrine changes around the placenta are particularly important for the survival of the pregnancy, whereas CCL-2 and fractalkine may be useful diagnostic markers of depression during pregnancy." (PMID 37892657, 2023). "Additionally, oxidative stress impairs energy metabolism, particularly in the energy-sensitive hippocampus, and promotes inflammation, as evidenced by elevated levels of chemokine motif chemokine ligand 2 (CCL-2) in depression, linked to cognitive deficits and abnormal Aβ metabolism in AD." (PMID 39981405, 2025). "In a fully adjusted model, depression was significantly associated with higher levels of IFN-γ and IL-1ra; IL-33, CCL-2, CCL-4 and TNF- α remained significant below the Bonferroni threshold." (PMID 39922907, 2025). "Some DEGs linked to depression and neuroinflammation (BDNF, CCL2 (Curzytek and Leśkiewicz, 2021), STC1, MEF2C) were also downregulated in Cit200 over time." (PMID 39055655, 2024). "Chemokines, such as the CCL2 (small chemokine from the CC-chemokine family), play a vital role in neuropsychiatric disorders, such as depression." (PMID 38674048, 2024). "In major depression, lower concentrations of CCL2 in blood serum were observed when compared to healthy controls." (PMID 38931342, 2024). "The alarmin IL-33, IL-17A, and the chemokine CCL2 have been highlighted in studies of depressive disorders, and their high production/expression was demonstrated in chronic T. gondii research in both experimental models and humans." (PMID 38835777, 2024). "The results revealed that depression patients’ plasma levels of CCL2, IL-6, IL-4 and IL-10 were all positively correlated." (PMID 37575572, 2023). "Our investigation revealed significant alterations in the peripheral levels of inflammatory factors—specifically IL-1β, IL-6, TNF-α, CRP, and CCL2—in individuals with major depressive disorder (MDD) presenting suicide-related behaviors." (PMID 37762207, 2023). "Results revealed that the classical pro-inflammatory cytokine TNF-α (p = 0.0011) and also the CCL2 chemokine (p = 0.0453), were significantly upregulated in depression patients compared with healthy controls." (PMID 37575572, 2023). "On the contrary, while CCL2 levels in plasma were found upregulated in depression patients, mRNA levels of this cytokine in PBMCs remained unaltered." (PMID 37575572, 2023). "Studies have reported that IL-6, TNF-α, CRP, YKL-40, IL-17, IL-1β, CCL2, IL-2, and IL‐8 are related to worse cognitive function or cognitive deterioration, while CRP, TNF-α, sIL-2R and CCL2 reflect severe symptoms of depression and anxiety." (PMID 36739284, 2023). "In this study, we found an upregulation of TNF-α and CCL2 levels in the plasma of depression patients." (PMID 37575572, 2023).